CENPA (centromere protein A)
Diseases named in the same sentence as CENPA in open-access papers (continued):
Sharing a sentence is not in itself a finding about the gene and the disease.
uveal melanoma (2 papers, 2024 to 2025). A melanoma derived from melanocytes of the uveal tract. "Notably, mesothelioma (MESO) and uveal melanoma (UVM) lacked comparable normal tissue, while acute myeloid leukemia (LAML) was the only cancer type where CENPA expression was lower in cancerous tissues than in normal tissues." (PMID 39820192, 2025).
B cell lymphoma (1 paper, 2022). "Subsequently, CENPA was witnessed to induce the transcription of Myc and to elevate the expression of B cell lymphoma-2." (PMID 35013138, 2022).
eye cancer (1 paper, 2025). "The analysis of single-cell data also suggested that CENPA was negatively correlated with DNA repair in eye cancer." (PMID 39820192, 2025). "In eye cancer (UVM), CENPA was not correlated with TMB but correlated with MSI." (PMID 39820192, 2025).
fibrosarcoma (1 paper, 2014). A malignant mesenchymal fibroblastic neoplasm affecting the soft tissue and bone. "We repeated this experiment in HT1080, a human fibrosarcoma cell line stably expressing GFP-centromere protein A (CENPA)." (PMID 24842991, 2014).
heart failure (1 paper, 2017). Inability of the heart to pump blood at an adequate rate to meet tissue metabolic requirements. "The modules related to nucleosome and chromatin assembly were associated only with heart failure arising from FCM, with increased HIST1H2BN, CENPA, HIST1H1A and HIST1H2AK." (PMID 29160422, 2017). "Epigenetic changes in FCM, such as increased HIST1H2BN, CENPA, HIST1H1A and HIST1H2AK, may thus be useful for distinguishing FCM from HCM and DCM and may also be a useful therapeutic target for patients with heart failure arising from FCM." (PMID 29160422, 2017).
kidney cancer (1 paper, 2021). Primary or metastatic malignant neoplasm involving the kidney. "In kidney cancer, many scholars have already screened out CENPA as a diagnostic and prognostic biomarker through bioinformatics analysis, including chromophobe and ccRCC." (PMID 34627268, 2021). "However, though researchers claimed that CENPA may play a role in kidney cancer through bioinformatics analyses, the relationship between CENPA and ccRCC has not been unearthed by in vitro experiment yet." (PMID 34627268, 2021).
neuroendocrine carcinoma (1 paper, 2024). A malignant neuroendocrine neoplasm composed of cells containing secretory granules that stain positive for NSE and chromogranin. "The Venn diagram showed that there were only two genes exclusively overexpressed in the high-grade MTC subset: DLL3, an inhibitory NOTCH pathway ligand associated with neuroendocrine carcinomas, and CENPA, a protein-coding gene associated with centromere function." (PMID 38958823, 2024).
oral cancer (1 paper, 2025).
papillary renal cell carcinoma (1 paper, 2022). A rare subtype of renal cell carcinoma, arising from the renal tubular epithelium and showing a papillary growth pattern, which typically manifests with hematuria, flank pain, palpable abdominal mass or nonspecific symptoms, such as fatigue, weight loss or fever. "This work focused on investigating the relation of centromeric protein A (CENPA) gene expression with prognosis of papillary renal cell carcinoma (PRCC)." (PMID 36163007, 2022).
prostate tumor (1 paper, 2023). "Compared to the normal tissue, the levels of CENPA, ADCK5, FOXM1, TFAP4, and MAPK were up-regulated in prostate tumor tissue, with a decrease in the expression of LGALS3 and BAG3." (PMID 36891298, 2023).
Sjogren syndrome (1 paper, 2021). An autoimmune disorder in which immune cells attack and destroy the glands that produce tears and saliva. "Finally, we identified and validated autoantigenic signals to SSB, CENPA, and keratin proteins in a cohort of individuals with Sjogren’s syndrome." (PMID 33986742, 2021).
cancer (146 papers, 2007 to 2026). A tumor composed of atypical neoplastic, often pleomorphic cells that invade other tissues. "The overexpression of CENPA in cancers inferred its pan-cancer potential as a diagnostic biomarker and a therapeutic target." (PMID 39820192, 2025). "The results demonstrated that 19 cancer types had AUCs exceeding 0.9, indicating an outstanding diagnostic power of CENPA." (PMID 39820192, 2025). "CENPA has been implicated in the progression of various types of cancer through multiple regulatory mechanisms." (PMID 40804263, 2025). "Single-cell analysis in this study suggested that CENPA was highly expressed during the S&G2 phase in the cell cycle and was closely associated with the G2/M checkpoint in cancer cells." (PMID 39820192, 2025). "CENPA serves as a crucial biomarker for the cell cycle in cancers, offering both diagnostic and prognostic value." (PMID 39820192, 2025). "To further validate the potential association between CENPA and cancer proliferation and cell cycle regulation, we analyzed the correlation between CENPA expression and cancer functional signals using multiple single-cell data sets across various cancer types." (PMID 39820192, 2025). "Given that our study demonstrated a close association between CENPA and the cancer cell cycle, patient survival, and the immune microenvironment, we proposed CENPA as a potential therapeutic target for cancer drug treatment." (PMID 39820192, 2025). "CENPA holds promise as a biomarker in cancers linked to cell cycle regulation and stemness, with significant potential for diagnostic, prognostic, and therapeutic applications." (PMID 39820192, 2025). "CENPA showed a strong association with the cancer cell cycle, particularly as a biomarker for the G2 phase." (PMID 39820192, 2025). "Five cancer types had AUCs ranging from 0.8 to 0.9, supporting the excellent diagnostic capability of CENPA." (PMID 39820192, 2025). "To delineate the transcriptional control of this module, we investigated associated TFs, highlighting the roles of prominent cancer‐associated TFs, such as CENPA, HNF1A, and E2F7." (PMID 39102671, 2024). "Similar to our finding, a previous study has also affirmed that CENPA is responsible for the amplification and overexpression of Myc, and further results in histone variant mislocalization of human cancer cells." (PMID 35013138, 2022). "CENPA expression was associated with higher drug resistance to nelarabine, asparaginase, dexamethasone Decadron, cladribine, and hydroxyurea in cancer cells." (PMID 36213834, 2022). "The IMvigor210 cohort was used to explore the underlying association between CENPA expression and cancer immunotherapy." (PMID 36341103, 2022). "Expression levels of CENPA are associated with patients’ responses to chemo- and radiotherapy and they predict poorer survival rates of cancer patients." (PMID 36012427, 2022). "Meanwhile, studies have discovered that overexpression of CENPA in cancer tissues is associated with poor clinicopathological factors, implying that CENPA most likely acts as an oncogene." (PMID 36163007, 2022). "The centromeric histone H3 variant CENPA is overexpressed in cancer and has the propensity to localize to genomic loci that lie outside of the canonical centromere in the setting of overexpression." (PMID 32371391, 2020). "The abnormal expression and loss of function of CENPA led to the destruction of genome integrity and abnormal cell division, which led to cancer." (PMID 33391344, 2020). "CENPA is a centromere-specific histone H3 variant overexpressed in cancer whose functional contributions to malignancy have remained elusive." (PMID 32371391, 2020). "Centromere protein A (CENP-A), an essential centromere protein, has been associated with high grade cancers." (PMID 22559056, 2012).
cancer (continued). "In this report we focus on the structure and function of CENPA in kinetochore assembly and centromere activity, and we detail the role of this histone variant in the developing of some human diseases such as cancer and autoimmunity." (PMID 20119530, 2009). "Additionally, three cancer types had AUCs between 0.7 and 0.8, reflecting an acceptable diagnostic power of CENPA." (PMID 39820192, 2025). "CENPA exhibited low levels of gene mutation across various cancers." (PMID 39820192, 2025). "The results indicated that CENPA expression was positively correlated with stemness across most cancer types, suggesting that the association with stemness might be a common mechanism of CENPA in cancer." (PMID 39820192, 2025). "Similarly, CENPA is essential for kinetochore assembly and chromosome segregation, with its overexpression leading to chromosomal instability, a hallmark of cancer." (PMID 39201599, 2024). "DAXX (Death Domain-Associated Protein), HJURP (Holliday Junction Recognition Protein) and CENPA (Centromere Protein A) proteins are implicated in epigenetic mechanisms, now in the spotlight of cancer research to better understand the molecular background of tumorigenesis." (PMID 39200236, 2024). "In addition, there is a direct correlation between overexpression of CENPA and genomic instability, which can cause cancer and promote disease progression." (PMID 36341103, 2022). "CENPA is a histone-H3 variant that regulates cell division by establishing kinetochore assembly and ensuring proper centromere segregation and is associated with cancer progression." (PMID 34966575, 2021). "To further investigate whether any particular cancer-specific enhancers were linked to patient outcome, we performed survival analyses using cancer-specific enhancer probes linked to CENPA, FOXM1, or MYBL2." (PMID 32925947, 2020). "Therefore, we examined the subgroup of LUAD samples, which had high expression of the three transcriptional regulators as well as many enhancer links (over 290 cancer-specific CENPA, FOXM1, or MYBL2 enhancer links), called “highly linked” samples for correlations to overall patient survival." (PMID 32925947, 2020). "Drugs such as CD-437, 3-Cl-AHPC, Trametinib, BI-2536, and GSK461364 were predicted to target CENPA in cancer cells." (PMID 39820192, 2025). "Recent studies uncovered that CENPA overexpression can reprogram cell fate and impact 3D nuclear organization in cancer." (PMID 40809351, 2025). "The initial analysis of this study focused on investigating CENPA genomic alterations in various cancers." (PMID 39820192, 2025). "Among all the ten single-cell cancer data sets analyzed, CENPA was highly expressed in a population of cell clusters that had strong signals of G2M checkpoint." (PMID 39820192, 2025). "The analysis identified T cell CD4+ as the most notable immune cell type correlated with CENPA; Th2 cells were positively correlated with CENPA across all cancer types, and Th1 cells were positively correlated in the majority of cancers." (PMID 39820192, 2025). "The results revealed that CENPA was correlated with several cancer-related pathways and biological processes." (PMID 40804263, 2025). "To explore the potential common functional effects of CENPA in cancers, we identified the top CENPA-correlated genes by analyzing data from all 33 TCGA cancer types as a single cohort." (PMID 39820192, 2025). "Since the effectiveness of cancer immune therapy largely depends on immune cell infiltration levels and the presence of immune checkpoints, we explored the value of CENPA as a predictive biomarker for immune therapy from these two perspectives." (PMID 39820192, 2025).
cancer (continued). "For example, disruption of CENPA-m6A-cenRNA interactions results in abnormal chromosome segregation and genomic instability in cancer cells, inhibits cancer cell growth, and enhances their sensitivity to mitogen-associated drugs." (PMID 40458727, 2025). "In clear cell renal cell carcinoma, the function of CENPA was reported to promote metastasis of cancer via the Wnt/β-catenin signaling pathway." (PMID 39820192, 2025). "The analysis demonstrated that CENPA was overexpressed in the majority of cancer types compared to normal tissues in both females and males." (PMID 39820192, 2025). "The staining images generally showed that, although CENPA staining intensity was slightly stronger in cancer tissues, the overall staining intensity in both cancerous and normal tissues was low, potentially due to the properties of the antibody used." (PMID 39820192, 2025). "Disrupting CENPA‐cenRNA interactions induces chromosomal instability, impairing tumor proliferation and offering a potential strategy for cancer therapy." (PMID 40657555, 2025). "The mRNA expression analysis of CENPA, utilizing data from TCGA and GTEx, revealed significant overexpression in 30 out of the 33 cancer types examined." (PMID 39820192, 2025). "To address this, we calculated immune cell infiltration levels in cancers and analyzed their correlation with CENPA expression." (PMID 39820192, 2025). "Most cancer types exhibited 20–40% of CENPA heterozygous amplification, and approximately half had 5–10% heterozygous deletion samples." (PMID 39820192, 2025). "CENPA promotes cancer progression and metastasis by accelerating the cell cycle and activating the Wnt/β-catenin signaling pathway." (PMID 41589308, 2025). "To explore this, we screened and predicted potential drugs targeting CENPA using cancer drug databases and computational methods." (PMID 39820192, 2025). "These correlation results were summarized (as shown in the top bar plot of S2E Fig) to provide an overview of CENPA’s potential common roles in cancers." (PMID 39820192, 2025). "To further understand CENPA’s specific role in different phases of the cell cycle in cancer cells, we analyzed single-cell expression data for CENPA across various cell cycle phases in U2OS cells, which predominantly express CENPA in the nucleus." (PMID 39820192, 2025). "The screening identified 8 drugs with sensitivities negatively correlated with CENPA levels in cancer cells and 4 drugs with sensitivities positively correlated with CENPA levels." (PMID 39820192, 2025). "This study used bioinformatic data to support the potential values of CENPA for clinical cancer diagnosis and prognosis." (PMID 39820192, 2025). "In this study, the mRNAsi (a measure of stemness) was calculated for 33 cancer types in the TCGA, and the correlation between CENPA expression and pan-cancer stemness was analyzed." (PMID 39820192, 2025). "The docking results revealed that CD-437, 3-Cl-AHPC, Trametinib, BI-2536, and GSK461364 had high binding affinities to CENPA, suggesting that these drugs are likely to directly target CENPA in cancer cells." (PMID 39820192, 2025). "Drug sensitivity data were obtained from the GDSC and CTRP databases, and the correlation between CENPA expression and the sensitivity of cancer cell lines to various small molecules and drugs was analyzed." (PMID 39820192, 2025). "Of note, elevated CENPA expression in multiple human cancer tissues, including breast, colon, and gastric, was identified by earlier studies, implying its nonnegligible association with cancer development." (PMID 39456925, 2024). "The analysis suggested that CENPA significantly affected other cancer‐related signalling pathways except for the Wnt signalling pathway." (PMID 39620895, 2024). "Using sequencing data from various cancers in the TCGA database, we conducted a pan‐cancer analysis of CENPA." (PMID 39620895, 2024).
cancer (continued). "The molecular profiling of CENPA in human cancer was analyzed by a Oncomine analysis, which indicated that CENPA is highly expressed in almost 20 types of solid tumors in contrast with normal tissue." (PMID 39456925, 2024). "In order to ensure a proper chromosome segregation in the process of malignant transformation, cancer cells require sufficient expression of CENPA." (PMID 39456925, 2024). "Among the biomolecules implicated in cancer epigenetics, DAXX, HJURP and CENPA represent three proteins heavily impacting oncogenesis in a variety of tumors." (PMID 39200236, 2024). "The aberrant expression or functional defect of CENPA leads to the interruption of genome integrity and abnormal cell division, thus inducing the emergence of cancer." (PMID 37059592, 2023). "Pan-cancer analysis revealed that Centromere Protein A (CENPA) and Metallopeptidase Inhibitor 1 (TIMP1) were highly expressed in most cancers and significantly associated with a poorer prognosis, also in ccRCC." (PMID 37213288, 2023). "In HCC cell lines profiled in the Cancer Cell Line Encyclopedia Project, we found that CENPA mRNA was generally highly expressed." (PMID 37928273, 2023). "When CENPA was knocked down, the levels of these cancer stem cell biomarkers were significantly decreased." (PMID 35816352, 2022). "It has been demonstrated that CENPA, MYBL2, and FOXM1 were linked to numerous cancer-specific enhancers, and their elevated expression levels were associated with a poor survival rate of NSCLC patients." (PMID 35721149, 2022). "Recent studies have documented that CENP-A overexpression promotes aneuploidy with karyotypic heterogeneity contributing to an aggressive phenotype in CENPA overexpressing cancers." (PMID 35955489, 2022). "Centromere protein A (CENP‐A) is a centromere specific variant of canonical histone H3 and indispensable for cancer progression." (PMID 35726713, 2022). "Subsequent evidence showed that upregulation of CENPA promoted initiation and progression in several cancers." (PMID 35518784, 2022). "Alternatively, there is a direct link between the elevated CENPA gene expression and genomic instability, a condition that also triggers cancer occurrence and promotes disease progression." (PMID 36163007, 2022). "We also determined CENPA levels within cancer and matched non-carcinoma samples through immunohistochemistry (IHC)." (PMID 36163007, 2022). "Due to CENPA overexpression in several types of cancers, it is expected to be a broad-spectrum anti-tumor target in clinical use." (PMID 34627268, 2021). "The immunohistochemistry (IHC) results of cancer/para-cancer pairs also suggested that CENPA was upregulated in cancer tissues." (PMID 34627268, 2021). "CENPA is overexpressed in several cancers, and plays an auxiliary but important role in cancer pathogenesis, progression, distant metastases and invasion angiogenesis, etc53,54." (PMID 34556750, 2021). "CENPA overexpression, driven by as-yet uncharacterized oncogenic events, thus potentiates uncontrolled proliferation in prostate and perhaps other cancers." (PMID 32371391, 2020). "Among the activated transcriptional regulators identified, CENPA, FOXM1, and MYBL2 were linked to numerous cancer-specific enhancers." (PMID 32925947, 2020). "Of the transcriptional regulators activated in LUAD, CENPA, FOXM1, and MYBL2 were linked to the activation of hundreds of cancer-specific enhancers." (PMID 32925947, 2020). "Diseases of uncontrolled cell division, particularly cancer, are thus compelling to examine from the epigenetic perspective of centromere biology, primarily as it pertains to the key epigenetic mark CENPA." (PMID 32371391, 2020). "Aberrant CENPA expression participates in multiple stages of cancer progression by regulating the cell cycle." (PMID 32391055, 2020). "An aberrant expression of CENPA and defects in CENPA function result in disrupted genome integrity, abnormal cell division, and thereby cancer." (PMID 32337237, 2020).